RN7SL215P (RNA, 7SL, cytoplasmic 215, pseudogene)
Gene: Miscellaneous RNA gene on chromosome 3 (194,145,674 to 194,145,971, forward strand). Ensembl gene ENSG00000242201.
Homologues: Orthologues: chimpanzee Metazoa_SRP (98% identical), macaque Metazoa_SRP (90% identical). Paralogues in human: RN7SL2 (79% identical), RN7SL786P (79% identical), RN7SL1 (79% identical), RN7SL126P (78% identical), RN7SL679P (78% identical), RN7SL47P (78% identical), RN7SL3 (78% identical), RN7SL357P (77% identical), RN7SL709P (77% identical), RN7SL296P (77% identical), RN7SL88P (77% identical), RN7SL322P (77% identical), and 699 more.